PVR (PVR cell adhesion molecule)
Diseases named in the same sentence as PVR in open-access papers (continued):
Sharing a sentence is not in itself a finding about the gene and the disease.
tumor (continued). "Since PVR is particularly expressed in lower-stage NB and PVRL2 is associated with advanced tumour stage, rapid progression, and high malignancy, both receptors are worth consideration in the evaluation of further therapeutical approaches." (PMID 40317320, 2025). "In fact, blocking the KIR2DL5/PVR interaction with monoclonal antibodies has been shown to enhance NK cell-mediated cytotoxicity against PVR+ tumors and reduce tumor growth, thereby improving overall survival in humanized tumor models." (PMID 40977889, 2025). "The positive correlations between PVR gene expression and its serum levels, with β2-microglobulin (rs = 0.813, p < 0.001; r = 0.441, p = 0.001) underscore the link between PVR and tumor burden, consistent with its role as a marker of disease activity." (PMID 40369504, 2025). "Specifically, epithelial cells in this group acted as the source of Poliovirus receptor (PVR or CD155) signaling, which dampens the anti-tumor activity of T cells." (PMID 40475762, 2025). "Interaction of TIGIT with PVR or PVRL2 on tumour cells leads to the inhibition of immune cells via the immunoreceptor tyrosine-based inhibitory motif (ITIM) domain." (PMID 40317320, 2025). "A study used mathematical modeling to explore the effects of inhibiting TIGIT, PVRIG, PVR, or their combinations on receptor engagement in immunological synapses (IS) between T-cells and tumor cells." (PMID 40567374, 2025). "Further analysis revealed that immune checkpoint genes CD47, PVR, SIRPA, and VTCN1 were found to be elevated in the high-risk cohort, indicating their role in suppressing anti-tumor immunity." (PMID 40243557, 2025). "Subsequent analysis showed markedly higher PVR transcript expression in VPS25high tumor cells relative to their low-expressing counterparts." (PMID 40149859, 2025). "TIGIT, CD226, CD96 and PVRIG are expressed on T and NK cells, whereas CD155 (PVR) is often overexpressed on tumour cells." (PMID 41462864, 2025). "KIR2DL5 functions as an inhibitory receptor by binding to PVR on tumor cells, promoting the formation of inhibitory synapses and suppressing NK cell cytotoxicity." (PMID 40977889, 2025). "Blocking FAK activity decreased tumor burden, suppressed ascites KMF-associated CD155/PVR levels, & increased peritoneal TILs." (PMID 40475770, 2025). "ZGGS15, a BsAb that blocks both LAG-3 and TIGIT, can potently inhibit LAG-3 and TIGIT receptors on immune cells by attaching to their specific binding ligands, MHC-II and PVR (CD155), on tumor cells." (PMID 38724599, 2024). "PVR expression was increased in surviving tumor cells after co-culture with TILs from the responder and inhibited TIGIT+ T cell activation." (PMID 39156900, 2024). "In BCG treatment, the mechanisms of immune-escape are diverse, including the loss of MHC-I or the up-regulation of PD-L1 and the poliovirus receptor (PVR or CD155) in tumor cells." (PMID 39682686, 2024). "Across most tumor types, there exists a robust correlation between PVR and NECTIN2 expression and infiltration of epithelial cells." (PMID 39120585, 2024). "In examining PVR expression and NK cell infiltration by IHC, PVR expressed on the plasma membrane strongly correlates with the tumor-infiltrating NK cells." (PMID 39156900, 2024). "The immunohistochemistry results from HPA database showed that PVR is significantly enriched in tumor tissues." (PMID 39474422, 2024). "CD96 interacts with PVR (CD155) expressed by tumor cells, similar to the interaction of TIGIT and DNAM1." (PMID 39339180, 2024). "Regarding tumor immunity, PVR expression was inversely correlated with tumor-infiltrating lymphocytes." (PMID 39156900, 2024). "The combination of PVR knockdown and Adriamycin administration induces more cell death and inhibits tumor growth than either one." (PMID 39156900, 2024).
tumor (continued). "TIGIT functions particularly strongly as a ligand for PVR and is highly expressed in tumor-infiltrating lymphocytes in many cancers, including endometrial, breast, renal cell, non-small cell lung, and colon cancer." (PMID 39156900, 2024). "In vivo, tumor rejection was notably diminished in mice lacking DNAM-1 expression, particularly in models where the DNAM-1 ligand PVR was expressed on tumor cells." (PMID 39273034, 2024). "Newer studies employing monoclonal antibodies against either DNAM-1 or PVR resulted in strong inhibition of tumor cell cytolysis." (PMID 39294470, 2024). "Our analysis revealed the correlation between PVR and NECTIN2 expression and the tumor immune microenvironment or tumor microenvironment in cancer, and further solidified the critical role of PVR and NECTIN2 in tumor immune regulation." (PMID 39120585, 2024). "Conversely, TIGIT, an immune checkpoint receptor found on both natural killer (NK) cells and T cells, reduces the activity of these immune cells by interacting with its ligand poliovirus receptor (PVR), located on antigen-presenting or tumor cells." (PMID 39050882, 2024). "In this section, we summarize the expression of PVRL2 and PVR in cancer and their effects on tumor immunoregulatory mechanisms." (PMID 39156900, 2024). "Poliovirus receptor (PVR), which can bind to multiple receptors to regulate the immune system and is known to promote tumor proliferation, is increased in cancer compared to precancer (p = 0.0003)." (PMID 39672307, 2024). "In mouse tumor models, simultaneous inhibition of the TIGIT/PVR and PD-1/PD-L1 pathways improved anti-tumor activity compared with blockade of either pathway alone." (PMID 38451273, 2024). "While PVRL2 and PVR are known to be expressed on many tumor cells, they are also expressed on immune cells and widely regulate cell-cell interactions." (PMID 39156900, 2024). "It has also been shown that decreased PVR expression induces cell apoptosis and inhibits tumor cell growth by inhibiting PI3K/Akt and MAPK signaling pathways." (PMID 39156900, 2024). "We observed that PVR-TIGIT interaction was enriched between tumor cells and Tregs in the papillary and solid patterns, implying that blockade of the PVR-TIGIT axis is a potentially effective treatment for LUAD patients with papillary and solid patterns." (PMID 39474422, 2024). "Among the Nectin and Necl family members, PVRL2 and PVR are critical players in tumor immunity, and immune checkpoint pathways mediated by them are potential therapeutic targets." (PMID 39156900, 2024). "Increased PVR expression in tumors is correlated with decreased activity of tumor-infiltrating lymphocytes (TILs) and a poorer prognosis across various cancer types." (PMID 39349829, 2024). "Mechanistically, these receptors with opposite effects compete to bind the same ligands, PVR and Nectin-2, which are highly expressed on tumor cells." (PMID 39126041, 2024). "PVR/CD155 also contributes to cancer progression by downregulating the immune response to tumor cells." (PMID 39335111, 2024). "PVR+PVRL2+ tumor cells are the most abundant compared to other cancers and have higher PVRIG expression." (PMID 39156900, 2024). "Concurrently, DNAM1 interacts with Nectin-5, Nectin-2, and the poliovirus receptor (PVR) on the surface of tumor cells." (PMID 39748921, 2024). "Based on a high-throughput ECD-interaction screening method called Conditioned Media Alpha Screening, KIR2DL5 (an orphan NK-cell protein) was identified to bind specifically with the poliovirus receptor (PVR) on tumor cells." (PMID 39872863, 2024). "In this section, we mainly summarize the functions of PVRL2 and PVR expressed on tumor cells, focusing on their immune system regulation." (PMID 39156900, 2024). "PVRL2 and PVR are predominantly expressed on tumor cells and antigen-presenting cells, binding to PVRIG and TIGIT, respectively, which are primarily found on T and NK cells, thereby suppressing antitumor immunity." (PMID 39156900, 2024).
tumor (continued). "We propose that high levels of PVR expression with advancing disease act to select for DNAM-1 upregulation but that cellular cytotoxicity is suppressed in the tumour microenvironment." (PMID 39835114, 2024). "Accordingly, DNAM-1-deficient mice showed increased tumor development and mortality after transplantation with tumors that express PVR, due to a reduction in the ability of NK and cytotoxic T cells to recognize and kill tumor cells." (PMID 37760586, 2023). "This pro-adhesive property of CD96 and a higher expression of PVR in certain tumors aids in tumor recognition and tumor cell death by NK cells." (PMID 36674817, 2023). "In our study, PVR expression exhibited distinct levels among molecular subgroups and non-tumor brain tissue." (PMID 36825029, 2023). "TIGIT blockade also restored most of the ability of PM21-NK cells to degranulate upon PVR+ cell restimulation post-tumor-co-culture." (PMID 37345049, 2023). "This down-modulation is probably due to sustained interaction with PVR expressed on the surface of ovarian carcinoma cells, since co-incubation of peripheral blood NK cells with tumor cells reproduces DNAM-1 down-modulation." (PMID 37760586, 2023). "Acetate suppressed the level of PVR/CD155 by inhibiting PI3K/AKT pathway to enhance the anti-tumor ability of CD8+ T cells." (PMID 37122756, 2023). "There are several clinical trials in progress targeting TIGIT and its receptor PVR to halt tumor progression." (PMID 37345111, 2023). "In a genetic model of spontaneous B-cell leukemia, the activation of the DNA damage response during the early stages of tumor progression is responsible for the expression of PVR that, in turn, is sufficient to activate T and NK cell-mediated tumor regression." (PMID 37760586, 2023). "In two HCC cell lines (HepG2.2.15 and MHCC-LM3), we found that blockade of PVR or PVRL2 increased immune cell-mediated lysis of tumour cell, with the combination group showing a higher enhancement effect." (PMID 37383234, 2023). "DNAM-1 is an activating receptor that binds PVR and Nectin2 adhesion molecules frequently overexpressed on the surface of cancerous cells, thus representing a central receptor in tumor recognition." (PMID 37760586, 2023). "Of note, the high expression levels of PVR, typical of various tumor types, revealed its hypothetical proto-oncogenic role, leading researchers to develop therapeutic strategies that directly target PVR." (PMID 37359555, 2023). "Altogether, these observations from functional and transcriptomic analyses demonstrated that TIGIT blockade restored PM21-NK cell anti-tumor functions against PVR+ cancer cells after exposure to cancer cell spheroids." (PMID 37345049, 2023). "Combining TIGIT blockade during tumor exposure with either PVR+ or PVR− restimulation allowed us to decern which function was negatively impacted by the engagement of the TIGIT/PVR pathway, and to what extent." (PMID 37345049, 2023). "Combining fludarabine with fusion proteins comprising the poliovirus receptor (PVR) and the programmed death-1 (PD-1) extracellular structural domain improves long-term tumor-specific immunosurveillance and CD8+ T cell-mediated anticancer effects." (PMID 37056756, 2023). "In vitro, antibody blockade of PVR or PVRL2 on HCC cell lines or TIGIT blockade on immune cells increased immune cell-mediated lysis of tumor cell." (PMID 37383234, 2023). "The genes PVR and NECTIN2, which encode for TIGIT ligands, were expressed by tumor epithelial, endothelial, fibroblasts, macrophages, and DCs in the TME." (PMID 38008725, 2023). "DNAM-1 specifically recognizes PVR and Nectin-2 ligands that are expressed on some virus-infected cells and on a broad spectrum of tumor cells of both hematological and solid malignancies." (PMID 37359555, 2023).
tumor (continued). "Previous studies have shown that PVR molecules expressed on the surface of tumor cells can bind to TIGIT on the surface of NK cells, which lead to inhibitory signals in NK cells, and then reduce the function of NK cells to kill tumor cells." (PMID 37035135, 2023). "Accordingly, in murine models of lung and breast cancer, increased expression levels of PVR on tumor cells is responsible for DNAM-1 down-modulation on both NK and T cells and correlates with tumor metastasization." (PMID 37760586, 2023). "In vitro, antibody blockade of PVR or PVRL2 on HCC cell lines or TIGIT blockade on immune cells increased immune cell-mediated lysis of tumour cell." (PMID 37383234, 2023). "TIGIT can bind to two different ligands expressed by tumor cells and APCs: CD155 (PVR), and CD112 (PVR2) with lower affinity." (PMID 37056774, 2023). "In tumors, the expression of PVR is also closely related to the degree of tumor differentiation and TNM stage." (PMID 36552960, 2022). "Endothelial and tumor cells mainly secreted poliovirus receptor (PVR) and NECTIN2, which acted on the TIGIT receptor on the surface of Tex." (PMID 36685571, 2022). "TIGIT ultimately suppresses anti-tumor immunity through binding to PVR and a subsequent series of responses." (PMID 36558902, 2022). "PVR is a member of the cell adhesion molecules (CAMs), and its abnormal expression has an important impact on the biological behavior of tumor cells." (PMID 36552960, 2022). "PVR, a member of the nectin-like family of adhesion molecules, has been proved to decrease the expansion and function of tumor antigen-specific CD8+ T cells." (PMID 35646872, 2022). "First, according to its endogenous function, overexpressed PVR supports proto-carcinogenic roles by promoting tumor cell invasion, migration, proliferation, and angiogenesis." (PMID 35625835, 2022). "Tumor cells also acquired TIGIT expression after relapse, leading to the enhanced interaction of tumor cell TIGIT with monocyte CD155/PVR." (PMID 36163179, 2022). "For example, PVR overexpression in tumor cells increases the activation of immune cells and tumor cell death through interaction with CD226." (PMID 35625835, 2022). "An increasing number of studies have demonstrated a relationship between PVR and tumor progression in recent years." (PMID 36552960, 2022). "To further understand the KIR2DL5/PVR pathway within the human tumor microenvironment, we analyzed data sets from the Gene Expression Omnibus database and BloodSpot databases." (PMID 36377656, 2022). "In HCC, PVR enhanced cell proliferation, migration, and invasion and promoted tumor survival and metastasis." (PMID 36552960, 2022). "The H-score of PVR membrane expression in tumor cells ranged from 0 to 300, with a small subset of negative tumors (5%, n=12/240)." (PMID 36544779, 2022). "More importantly, the expression of PVR/TIGIT appears to be essential for the suppressive activity of Tregs in the tumor microenvironment." (PMID 36552960, 2022). "The conserved tumoral PVR proteins represent known tumor evasions strategies and can activate or inhibit NK cells and T cells." (PMID 36092893, 2022). "A previous study also showed that elevated PVR/TIGIT expression was associated with a reduction in IFN-γ, but was not necessarily correlated with reduced CD8+ T cell infiltration in the tumor before immunotherapy." (PMID 36552960, 2022). "PVR is a member of the laminin-like family, which not only promotes tumour progression and metastasis but also involves immunomodulation." (PMID 35069971, 2022). "The results showed that the expression of PVR in HCC tumor tissues was higher than that in adjacent tissues (p < 0.001)." (PMID 36552960, 2022). "Our findings indicated that in TNBC, TIGIT (expressed in cells located in the microenvironment) can easily interact with its receptor PVR (expressed on tumor cells) to induce immunosuppression." (PMID 36544779, 2022).
tumor (continued). "TIGIT contains three ligands, of which PVR (CD155), expressed in tumor cells and APC, is the main ligand for TIGIT with high affinity." (PMID 36558902, 2022). "A previous study demonstrated significantly higher levels of soluble PVR in patients with cancer relative to healthy donors, with these levels positively correlated with tumor stage." (PMID 35625835, 2022). "Analysis of the PVR pathway regulatory network showed that tumor and endothelial cells were the main senders, and immunosuppressive cells such as Tex were the receivers." (PMID 36685571, 2022). "We also found that tumors with higher expression of LSM12, LSM14A, and LSM14B had higher expression of tumor-related immune checkpoints (e.g., PD-L1, B7-H3, and PVR), which are important for the immunosuppressive phenotype in malignancies." (PMID 35646684, 2022). "In several preclinical models, blocking the PVR-TIGIT axis restored the anti-tumor immunity through T and NK cell activation and regulatory T cell inhibition." (PMID 36544779, 2022). "Of note, higher expression of tumor-related immune checkpoints (e.g., PD-L1, B7-H3, and PVR) was also observed in tumors with LSM12, LSM14A, and LSM14B overexpression." (PMID 35646684, 2022). "Our results demonstrated that KIR2DL5 functioned as an inhibitory receptor on NK cells and mediated PVR+ tumor immune resistance." (PMID 36377656, 2022). "Binding of TIGIT to CD155 (poliovirus receptor PVR) expressed on tumor cells results in the decreased secretion of pro-inflammatory cytokines such as IFN-γ, IL-17a, and TNF-α, and an increased secretion of the anti-inflammatory cytokine IL-10." (PMID 35345849, 2022). "TIGIT expression was observed in immune cells from the tumor microenvironment, whereas PVR was mainly expressed by tumor cells." (PMID 36544779, 2022). "Upon incubation with anti-KIR2DL5 blocking mAb F8B30, KIR2DL5+ NK cells manifested more potent cytotoxicity, degranulation (CD107a), and functional cytokine (IFN-γ and TNF-α) production after coculturing with PVR+ A427 or Jurkat tumor cells." (PMID 36377656, 2022). "The expression level of PVR was quantified using the Tumor and Tumor Immunity Evaluation Resource (TIMER) and Sangerbox." (PMID 36552960, 2022). "In contrast, TIGIT and CD96 are inhibitory receptors, and PVR upregulation in heterogeneous tumor cells results in tumor cell recognition and binding by activating receptor CD226 and the inhibitory receptors TIGIT and CD96." (PMID 35625835, 2022). "Taken together, these results demonstrated that KIR2DL5 inhibited NK cell function and facilitated tumor immune evasion through the engagement with PVR on tumor cells." (PMID 36377656, 2022). "While the presence of KIR2DL5 dramatically suppressed NK cytolytic activity against PVR+ tumor cells (scrambled control), this effect was eliminated upon the deletion of PVR in tumor cells by CRISPR/Cas9 (PVRKO)." (PMID 36377656, 2022). "Immunohistochemical staining data of tissues showed that the PVR protein expression was much higher in the tumor region than the paracancerous tissue." (PMID 36552960, 2022). "PVR is highly expressed not only by tumor cells but also by some immune cell subsets, including DCs." (PMID 36377656, 2022). "In IS-high samples, increased expression of PD-L1 (27.9% in IS-low vs. 48.2% in IS-high; p = 0.0336), HLA-E (73.8% vs. 90.7%; p = 0.0282) and PVR (70.5% vs. 87.0%; p = 0.0415) on tumor cells was detected." (PMID 34135436, 2021). "Meanwhile, we also analyzed the expression of CD47 and PVR on CT26 tumor cells derived from the tumor tissues." (PMID 34068552, 2021). "DNAM-1(DNAX accessory molecule-1) is another activation receptor expressed on γδ T cells that bind to poliovirus receptor (PVR/CD155), and Nectin-2 ligands, which are commonly upregulated on tumour cells." (PMID 33923528, 2021). "PVR was initially identified as the receptor for the human poliovirus, or as an adhesion-related molecule that mediates tumor invasion." (PMID 34068552, 2021).